BRAF (B-Raf proto-oncogene, serine/threonine kinase)
Diseases named in the same sentence as BRAF in open-access papers (continued):
Sharing a sentence is not in itself a finding about the gene and the disease.
tumor (continued). "Meanwhile, a different study found that increased tumor size, extrathyroidal extension, lymph node involvement and BRAF V600E mutations were major risk factors for poor prognosis." (PMID 38248796, 2024). "The application of BRAF inhibitors has shown promise in reversing tumor-associated immunosuppressive signals." (PMID 39061208, 2024). "In fact, the Lifileucel study demonstrated TIL efficacy in patients with BRAF mutations that showed tumor progression while being treated with BRAF inhibitors." (PMID 39682188, 2024). "The mCRC with dMMR/MSI-H is a highly immunogenic tumor subtype with unique pathological features such as right-sided primary, mucinous, poorly differentiated tumors and higher incidences of BRAF mutations." (PMID 39193390, 2024). "The identified transcriptomic signatures (clusters A and B) were associated with tumor diagnosis (tumor type; p < 0.0001), age at diagnosis (p = 0.018), mitotic index (p = 0.0478), and presence of the BRAF mutation (p = 0.0017)." (PMID 39766071, 2024). "A better understanding of the molecular mechanisms underlying the BRAF pathway and the tumor microenvironment associated with these mutations is essential for accurately characterizing and targeting non-V600 mutations." (PMID 39684685, 2024). "Our study showed that the presence of mutated BRAF ctDNA and high levels of the tumor marker S100B in early postoperative blood samples predicted the highest probability of disease recurrence and the worst prognosis." (PMID 39387479, 2024). "The aim of this research is to study the association of the proportion of tumor cells with BRAF V600E coding allele and the dissemination of the disease." (PMID 38540091, 2024). "The defective MMR protein expression in tumor tissue can be attributable to germline or somatic mutation in another DNA repair or replication-associated gene, such as BRAF, POLE/POLD1, or less frequently, MUTYH." (PMID 38297350, 2024). "We conducted an extensive literature search utilizing Medical Subject Headings keywords, namely “BRAF”, “mutation”, “lung”, “tumor”, “NSCLC”, and “neoplasm”, across multiple databases, including PubMed, EMBASE, ISI Science Citation Index, and CNKI." (PMID 38394545, 2024). "Conversely, a higher frequency of mutations in BRAF has been reported in tumor samples of patients of Caucasian ethnicity when compared with samples from Asian and African American subjects and between the Western and Chinese populations." (PMID 38731914, 2024). "BRAF-mutated ctDNA was detected in 42.1% of the samples and was positively correlated with tumor size, multifocal disease, gross extrathyroidal extension, and the presence of lung micrometastases." (PMID 39336882, 2024). "While the GSEA similarly identified increased KRAS signaling in this case, this tumor harbors a BRAF mutation, downstream of KRAS." (PMID 38791940, 2024). "The second patient with a biologically more favorable tumor profile (PXA) was characterized by the BRAF V600E mutation." (PMID 38326438, 2024). "This includes assessing additional mutational and clinico-pathological features, like BRAF status and tumor sidedness, and developing novel technologies to capture the dynamic genomic heterogeneity of mCRC under targeted treatment." (PMID 38667537, 2024). "The original cancer cfDNA sample had a cVAF of 1.1% as measured by droplet digital PCR (ddPCR) of a BRAF V600E mutation present in the primary tumor (Fig. EV3B)." (PMID 39164471, 2024). "B-raf proto-oncogene serine/threonine kinase (BRAF) V600E mutations have been observed in malignant renal glomus tumors, which can be utilized as a potential tumor agnostic therapy." (PMID 38449999, 2024).
tumor (continued). "Multiple studies have demonstrated that the presence of the BRAF mutation is linked to more aggressive tumor behavior, higher recurrence rates, and poorer overall survival." (PMID 39767732, 2024). "The positive prognostic role of cytotoxic T cells remained statistically significant in a multivariable analysis including gender, age, localisation, tumour stage, BRAF mutation, KRAS mutation, and MSI status." (PMID 38040818, 2024). "The most common mutation in the BRAF gene is the V600E mutation, which accounts for the majority of BRAF mutations across various tumor types." (PMID 39529955, 2024). "Thirteen METIMMOX patients had tumour with BRAF V600E/D mutation, of whom ten were randomly allocated to the control arm and had median PFS 3.7 months (95% CI, 3.0–7.3)." (PMID 38664577, 2024). "Other, less common somatic variants, such as those affecting the TR4 protein and the BRAF V600E gene variant, also contribute to tumor growth and hormone production through various signaling pathways." (PMID 39512978, 2024). "This rarity suggests that a single activating mutation in either NRAS or BRAF is typically sufficient to catalyze the pathway’s activity toward tumor development." (PMID 38534742, 2024). "TERTp and BRAF mutations were associated with aggressive clinicopathological features and tumor progression in PTCs (p < 0.001)." (PMID 38337794, 2024). "BRAF, a serine/threonine protein kinase that functions as a proximal effector of the MAPK pathway downstream of RAS, is also commonly mutated in histologically unrelated human tumors, making BRAF another tumor-agnostic target." (PMID 38920700, 2024). "In both cases and controls, the distributions of previous chemotherapy lines, ECOG score, proportion of RAS or BRAF mutation, and primary tumor location were the same." (PMID 38476223, 2024). "BRAF V600E in pLGGs is associated with a worse OS, the tendency of multiple progressions, and late deaths related to tumor progression, even at 25 years of follow-up." (PMID 39590171, 2024). "The study also identifies significant correlations between the BRAF mutation and clinical and histological features, contributing to a better understanding of tumor biology." (PMID 39767732, 2024). "Inferior OS was also observed for patients with CDX2-negative (N = 8) compared to CDX2-positive (N = 157) tumours when adjusted to exclude samples with the BRAF p.V600E variant (median 18 versus 103 months, respectively; Mantel-Cox log-rank test, p = 0.043)." (PMID 38439814, 2024). "Mutations in the BRAF gene can lead to persistent activation of the pathway, resulting in uncontrolled cell proliferation and tumor development." (PMID 39529955, 2024). "Association of overall survival (OS) and disease‐free interval (DFI) with first postoperative plasma levels of S100B tumor marker in combination with BRAF mutation status." (PMID 39387479, 2024). "There are frequent genomic alterations in these neoplasms, especially in the mitogen-activated protein kinase pathway, including BRAF (notably BRAF V600E), MAP2K1, KRAS, and NRAS mutations, and ALK gene translocation." (PMID 38713245, 2024). "Randomization was stratified according to BRAF mutational status, metastasis stage and PD-L1 expression in the tumor." (PMID 39727691, 2024). "A minimal set of variables linked to BRAF mutations, defined by the genetic input selection algorithm, included patient age, primary tumor location, histological type, lymphovascular invasion, ulceration, and association with nevi." (PMID 39735251, 2024). "For all plasma samples (n = 309) from patients who had RAS/BRAF-mutant tumors, the cfDNA tumor burden was determined using the mutant allele frequency (MAF) of the tumor-informed RAS/BRAF mutation as measured by ddPCR." (PMID 39433569, 2024). "BRAF mutation is also frequently observed in specific tumor subtypes, such as those with MSI-high MSI-H or CIMP features." (PMID 39273409, 2024).
tumor (continued). "A BRAF V600E mutation detected was deemed pathogenic following discussion at a molecular tumour board, and recommendation of further investigations led to the diagnosis of an occult haematological malignancy." (PMID 39516362, 2024). "In contrast, DN with BRAF V600E mutations had longer telomeres, indicating that these cells resulted from fewer divisions after tumor initiation than those in their counterparts driven by other MAPK mutations." (PMID 38371417, 2024). "This is especially important when a large lymphocytic infiltrate is present, as in the case of Hashimoto’s thyroiditis, where mutated, tumor-originating BRAF alleles become “diluted” by wild-type alleles originating from infiltrating lymphocytes." (PMID 38540091, 2024). "Through the consensus, clinicians can better understand the role of BRAF mutations in tumor development, select the most appropriate detection methods, and provide personalized treatment plans for patients." (PMID 39529955, 2024). "Immunohistochemistry shows positivity for S100, CD1a, and Langerin in the tumor cells; genetic testing reveals BRAF gene mutations in more than 50% cases." (PMID 38706599, 2024). "The BRAF V600E mutation induces aggressive tumor biology and is associated with right-sided colon tumors, poor differentiation, and metastatic disease." (PMID 39684219, 2024). "If eligibility for germline testing is instead based upon the NHS National Genomic Test Directory (indication R210), this includes all patients whose MLH1-deficient/MSI-High tumours are BRAF wild-type (i.e. skipping MLH1 promoter methylation testing)." (PMID 38355963, 2024). "Several tumor factors are believed to be crucial, such as the existence of oncogenic BRAF or NRAS mutations." (PMID 38339344, 2024). "A specific metabolic gene signature was identified as a hallmark of BRAF-mutated tumours, which display a glycolytic phenotype, characterised by enhanced glucose uptake, lactate efflux and increased expression of Hif-1α-modulated glycolytic genes." (PMID 37198319, 2023). "Several characteristics, including tumor location (p < 0.001), BRAF V600E mutational status (p < 0.001), MSI status (p = 0.002), and combined cytotoxic agents (p = 0.002), were imbalanced between the two groups." (PMID 37641470, 2023). "The molecular analysis of the tumour identified a BRAF V600E mutation at time of progression of relapsed disease under third line systemic treatment." (PMID 37417899, 2023). "Higher CD44 expression was associated with clinically poor prognostic features: age ≥ 70 years (p = 0.0166); inoperable disease (p = 0.0008); stage IV at diagnosis (p = 0.0241); BRAF mutated (p = 0.0111), high-grade tumor (p = 0.0084)." (PMID 36831554, 2023). "Treating a tumor caused by the BRAF V600E mutation with a combination of the drugs dabrafenib and trametinib has been shown to inhibit or reduce tumor growth." (PMID 37502629, 2023). "RAS and BRAF mutations are found in 50 and 5–20 per cent of tumours respectively in patients with metastatic colorectal cancer." (PMID 36511370, 2023). "To better study the role of these co-driver alterations, we assembled a large paediatric and adult cohort of 29 tumours H3K27-altered with co-occurring activating mutation in BRAF or FGFR1 as well as 31 previous cases from the literature." (PMID 38066305, 2023). "90% of the tumor volume was reduced using the BRAF inhibitor and the BRAF-mutated alleles also appeared in significantly lower frequency." (PMID 37115331, 2023). "Variants detected by NGS considered inconsistent with WHO tumor type predominantly occurred as BRAF or MYBL1 alterations in HGG defined by WHO criteria (8/14)." (PMID 36928815, 2023). "To address the limitations of current diagnostic options, we developed an assay for detecting canine UC that uses droplet digital PCR (ddPCR) analysis to detect the BRAF V595E mutation in exfoliated tumor cells recovered from urine specimens." (PMID 37079639, 2023).
tumor (continued). "Similar findings outside the data reviewed reported larger cases of MBMs and worse neurological symptoms among patients with tumor BRAF mutations compared to their wild-type counterparts." (PMID 36983983, 2023). "As for the specific CNAs that differ between the tumor groups, the gains at 1q, 3p, and 17q appear to occur less commonly in BRAF-mutated tumors whereas the losses at 10q are found more commonly in this tumor group." (PMID 37761808, 2023). "Previous studies have shown that gangliogliomas with BRAF-V 600E mutation have an increased risk for progression or recurrence especially in tumor located in the brainstem with a shorter progression free survival compared to BRAF wild-type gangliogliomas." (PMID 37936887, 2023). "Both binary and semi-quantitative approaches have found links between primary tumour BRAF and TERT promoter mutations and avidity in metastatic lesions." (PMID 37284971, 2023). "Early in the genomics era, the prevalence of BRAF V600 mutations was reported in 43 tumor types across 2963 samples in an AACR GENIE database." (PMID 37124503, 2023). "The slow-growth tumor phenotype induced by the initiation of the BRAF p.V600E mutation seems to be partially reversible due to the additional molecular abnormalities that guide a more aggressive evolution." (PMID 36831610, 2023). "BRAF mutant tumors also tend to have a lower average tumor mutational burden (TMB) than BRAF wildtype patients." (PMID 37403699, 2023). "This supports the suggestion that cholesterol plays a critical role in tumor metastatic promotion with the presence of the BRAF mutation." (PMID 37446330, 2023). "The patient was treated with mFOLFOXIRI-bevacizumab on October 2, 2020 after genetic testing revealed BRAF V600E mutation in the tumor tissue." (PMID 37409251, 2023). "BRAF mutations induce self-activation of downstream genes, which cause tumor cell growth and accelerated proliferation." (PMID 37927605, 2023). "Heterogeneity expression of MUC5B and other mucins were associated with BRAF somatic mutation, tumor location and mismatch repair deficiency." (PMID 37726835, 2023). "Molecular analysis revealed the exclusive presence of the BRAF K601E mutation in both primary tumor and metastatic lesions." (PMID 38002585, 2023). "There were many predictive models for assessing CLNM possibility in cN0 PTMC, but their models only incorporated clinical baseline data such as tumor characteristics, ultrasound and CT examination features or just included BRAF mutation result." (PMID 36817603, 2023). "RAS-mutated tumours are associated with a worse prognosis than RAS and BRAF wild-type tumours, which is also due to intrinsic resistance to the anti-EGFR agents cetuximab and panitumumab." (PMID 37297026, 2023). "This is, 48% of APC wild-type tumours were BRAF mutated in the bevacizumab treatment arm, whereas in the cetuximab treatment arm, only 29% were BRAF mutated (p = 0.13, Fisher’s exact test)." (PMID 37666855, 2023). "A relationship between BRAF mutations and lipid metabolites has previously been associated to tumor progression; also relevant is the concept of tumour-induced platelet activation." (PMID 38076065, 2023). "This analysis, other than corroborating the anti-glycolytic effect of VMR also in other BRAF-mutated tumour types, uncovered also a previously unrecognised repressive effect on genes belonging to lipid, nucleotide and amino acid metabolism pathways." (PMID 37198319, 2023). "Ulixertinib (BVD-523) was demonstrated to have robust anti-tumor activity in the preclinical models of the BRAF-mutated tumor, including those that had acquired resistance to BRAF/MEK-targeted therapy." (PMID 37370834, 2023). "RNF43 and BRAF mutations are molecular events involved in serrated tumour pathways during CRC development." (PMID 37409251, 2023).
tumor (continued). "Though works have suggested BRAF mutation as a risk factor for tumor aggressiveness and HT as a protective factor against tumor aggressiveness, few works have investigated the two simultaneously." (PMID 37190300, 2023). "The authors suggested that tumor inhibition was driven by MEK in BRAF-mutant models and by Aurora kinases in models mutated for KRAS." (PMID 37830744, 2023). "Among MSI CRC subgroups, acidic N-glycans showed tumor stage and BRAF mutation status-dependent variation." (PMID 37509233, 2023). "Further studies are needed to explore the functional implications of additional BRAF mutations, their relationship with histological pathways and tumor behaviors, and their potential role in treatment resistance." (PMID 38021761, 2023). "Another study based on east China also reported that BRAF mutation is correlated with larger tumor size, higher probability of PTC recurrence and LNM." (PMID 37081757, 2023). "The study revealed that age >45 years, body mass index ≥25, tumor size ≥1 cm, BRAF V600E mutation, and capsular invasion are the related risk factors for CLNM in patients with PTC." (PMID 38047112, 2023). "Based on the tumor RAS/BRAF mutational status, therapies involving anti-EGFR monoclonal antibodies (cetuximab, panitumumab) can be used." (PMID 38008721, 2023). "For 744 CRC cases, tumor tissue was available and successfully analyzed for the BRAF V600E mutation, KRAS mutations, or MSI status." (PMID 37849011, 2023). "The respective contributions of the BOREALIN and BRAF mutations to tumor development in the patient cannot be determined from our data." (PMID 37964961, 2023). "The mutation BRAF p.V600E was also investigated and confirmed in PCR on the post-therapy tumour biopsy." (PMID 37417899, 2023). "BRAF V600E mutation in thyroid malignancies is associated with an aggressive phenotype with more rapid tumor growth and higher mortality." (PMID 36819948, 2023). "For example, areas with papillary growth, smooth and pushing tumour fronts and urothelial differentiation were often predicted as being BRAF V595 positive (i.e., BRAF mutated)." (PMID 37570213, 2023). "By testing serial dilutions of tumor DNA samples with Tier I/II variants (BRAF V600E, KRAS G12C, and EGFR exon 19 deletion p.L747_E749del), the LOD for accurate and reproducible variant calling was determined to be 5% of variant allele frequency." (PMID 37483495, 2023). "The efficacy of BRAF inhibitors depends on triggering a cancer cell death program associated with an impact on the tumor immune microenvironment." (PMID 37838724, 2023). "The large heterogeneity of target genes explains the use of small inhibitory molecules (BRAFi) that specifically target BRAF V600 mutations leading to tumour regression." (PMID 37627054, 2023). "In the oncogenic BRAF-V600E mouse model, deletion of the tumour suppressor SMAD4 promoted rapid development and the progression of serrated tumours, and SMAD4 mutations co-occurred with BRAF-V600E mutations in human patient tumours." (PMID 37685308, 2023). "Regardless of the type of treatment (i.e., single agent or combined therapy), the BRAF/MEK inhibitor therapy is associated with a response rate of almost 100% with a tumor volume reduction ranging from 80–90% after 3–4 months of treatment." (PMID 36979325, 2023). "Of the CRC cases with molecular tumor data, 20% were BRAF mutated, 23% were KRAS mutated, and 13% were MSI." (PMID 37849011, 2023). "The BRAF-V600E gene mutation is a prevalent genetic alteration found in this tumor and is considered to have a crucial role in its pathogenesis." (PMID 37646022, 2023). "Based on previous studies in other tumor types, the p.V600E mutation was predicted to make tumor cells sensitive to BRAF inhibitors." (PMID 37140883, 2023). "The combination of the BRAF inhibitor dabrafenib and the MEK inhibitor trametinib carry a tumor-agnostic FDA indication for patients with tumors harboring a BRAF V600E mutation based on two basket trials." (PMID 37980380, 2023).